LINC00685 (long independently transcribed non-coding RNA 685)
Synonyms: OTTHUMT00000055574; formerly CXYorf10; NCRNA00107; PPP2R3B-AS1
Gene: Long non-coding RNA gene on chromosome X (320,990 to 321,851, forward strand). Ensembl gene ENSG00000226179.
Diseases named in the same sentence as LINC00685 in open-access papers:
LINC00685 is named in the same sentence as 1 disease in open-access papers, as found by Europe PMC text mining. Sharing a sentence is not in itself a finding about the gene and the disease. The quoted sentences say what the papers report.
hepatocellular carcinoma (1 paper, 2025). A malignant tumor that arises from hepatocytes. "This indicates that LINC00685 and GIHCG have high diagnostic values for hepatocellular carcinoma patients." (PMID 40792280, 2025).